SPDYE2B (speedy/RINGO cell cycle regulator family member E2B)
Synonyms: SPDYE2L
Tractability: No criterion of Open Targets' tractability assessment is met for any kind of drug.
Gene: Protein-coding gene on chromosome 7 (102,650,319 to 102,662,625, forward strand). Ensembl gene ENSG00000173678.
Gene Ontology:
Molecular function: protein kinase binding
Homologues: Orthologues: chimpanzee SPDYE6 (88% identical), mouse Spdye4a (33% identical), rat Spdye4 (33% identical), mouse Spdye4b (29% identical). Paralogues in human: SPDYE2 (99% identical), SPDYE6 (99% identical), SPDYE5 (96% identical), SPDYE21 (94% identical), SPDYE1 (89% identical), SPDYE18 (82% identical), SPDYE16 (82% identical), SPDYE3 (62% identical), SPDYE12 (55% identical), SPDYE13 (55% identical), SPDYE14 (55% identical), SPDYE15 (55% identical), and 6 more.
Diseases named in the same sentence as SPDYE2B in open-access papers:
SPDYE2B is named in the same sentence as 1 disease in open-access papers, as found by Europe PMC text mining. Sharing a sentence is not in itself a finding about the gene and the disease. The quoted sentences say what the papers report.
tumor (1 paper, 2025). "A high abundance of Hafnia and SPDYE2B was associated with worse DFS, suggesting that, for subsets of TNBC patients, these features may synergize in influencing tumor biology and patient outcomes." (PMID 40781241, 2025).